ALB (albumin)
Diseases named in the same sentence as ALB in open-access papers (continued):
Sharing a sentence is not in itself a finding about the gene and the disease.
delirium (continued). "In the present study, old age, low albumin level, poor cognitive function, and high pain score were identified as risk factors of emergence delirium; which were in accord with previous studies." (PMID 32507939, 2020). "Increased number of acute diseases and serum albumin concentration were also associated with delirium." (PMID 33071932, 2020). "Two previous studies have reported that a low serum albumin level is a risk factor for postoperative delirium." (PMID 33137161, 2020). "In this study, advanced dementia, low albumin levels, delirium and pressure ulcers were associated with increased in-hospital and 12 month mortality." (PMID 29694607, 2018). "Low albumin, high or low sodium and urea/creatinine ratio abnormality were most commonly associated with increased delirium risk." (PMID 24610863, 2014). "In pooled analysis, low albumin was statistically significantly associated with delirium (MD −3.14, 95% CI −5.99, −0.29, P = 0.03)." (PMID 24610863, 2014). "In patients with delirium, higher albumin levels were associated with shorter hospital stays." (PMID 41522719, 2026). "Additionally, clinical studies employing the cerebrospinal fluid-to-plasma albumin ratio (CPAR) to evaluate BBB dysfunction revealed that increased postoperative BBB permeability was associated with delirium incidence." (PMID 39857699, 2025). "This study aims to examine the association between preoperative serum albumin levels and postoperative delirium (POD) in geriatric patients who have undergone hip fracture surgery, with the goal of offering novel insights for clinical interventions targeting POD." (PMID 38420358, 2024). "Unadjusted and adjusted association between preoperative albumin levels and postoperative delirium." (PMID 38420358, 2024). "The regression analysis adjusted for multiple covariates (including age, gender, MMSE, albumin, phosphorus, renal function, and thiazide diuretic treatment) demonstrated that hypomagnesemia was independently associated with an increased risk of delirium." (PMID 36709228, 2023). "Similarly, we found the decrease in albumin level is a risk factor of developing delirium in CICU patients." (PMID 36937934, 2023). "This study intended to explore whether albumin-associated inflammatory and nutritional markers could predict post-operative delirium (POD) in older patients after total hip arthroplasty (THA)." (PMID 38024358, 2023). "The univariate analysis with the Mann–Whitney–U and x2 tests shows a statistically significant correlation between the development of delirium and fluid intake (p = 0.004), blood loss (p = 0.003), duration of ventilation (p = 0.019), duration of surgery (p = 0.036), and albumin levels (p = 0.039)." (PMID 35804948, 2022). "In standard blood tests, the included biomarkers are albumin and creatinine, and may be useful in identifying an increased risk of delirium, since low albumin levels appear to be associated with an increased risk of delirium in postsurgical patients." (PMID 36013306, 2022). "After analyzing 33 articles the following risk factors indicated a significant association with postoperative delirium: Age (>65 years), female sex, number of medications used preoperatively, low preoperative hematocrit, albumin, duration of surgery and intraoperative blood loss." (PMID 31117234, 2019). "In addition, albumin levels can be affected by a variety of factors, such as infection and underlying disease, potentially confounding the relationship between albumin and delirium." (PMID 38263028, 2024). "In addition, the postoperative loss of albumin and hemoglobin and long-term drainage are the risk factors for complications such as surgical site infection, hemorrhagic anemia, and delirium after PLIF." (PMID 37480018, 2023). "The lactate/albumin ratio (LAR) has emerged as a potential biomarker reflecting metabolic and nutritional status, serving as an indicator for delirium risk." (PMID 41995228, 2026).
delirium (continued). "More research is needed to explore the specific physiological mechanisms linking albumin and lymphocytes with delirium." (PMID 40765739, 2025). "Lower albumin levels (adjusted OR: 0.91) were inversely associated with POD, reflecting the role of nutritional status and systemic inflammation in delirium risk." (PMID 40301442, 2025). "Consequently, this research aimed to explore potential risk factors contributing to postoperative subsyndromal delirium in elderly patients with hip fractures and to examine whether low albumin levels are associated with postoperative subsyndromal delirium as well as patient outcomes after surgery." (PMID 41488107, 2025). "Key parameters were evaluated and compared, including serum IgA, IgG, IgM levels, total protein (TP), albumin (ALB), postoperative delirium incidence, nutritional status, recovery time, and overall patient outcomes." (PMID 40837358, 2025). "Previous studies had identified associations between dysphagia and variables such as age, sex, neurological disease, cardiac disease, low serum albumin levels, and the presence of delirium after hip fracture surgery." (PMID 38263028, 2024). "We observed a significant 2.3-fold increase in delirium among patients who received albumin replacement." (PMID 39679665, 2024). "Lu and colleagues assessed the prognosis of PD patients undergoing deep brain stimulation (DBS) using the fibrinogen-to-albumin ratio (FAR) and found that high FAR levels were independently associated with postoperative delirium after DBS surgery." (PMID 39286804, 2024). "Our study showed that patients with delirium after surgery had low serum albumin and high levels of fibrinogen." (PMID 38707190, 2024). "A univariate regression analysis of delirium showed significant differences between the PS (p = 0.02), preoperative albumin level (p = 0.02), and age (age 75 years or older) of patients (p = 0.02) with and without EPOD." (PMID 37232788, 2023). "Critically ill patients with ICU-delirium had significantly lower platelet counts (p < 0.001), lower oxygenation index (p = 0.007), and lower serum-albumin (p < 0.001)." (PMID 37854697, 2023). "Polypharmacy (more than five drugs) in the study group showed a low correlation to the duration of the perioperative delirium (r = 0.16), while higher blood albumin levels (r = −0.17) and younger age (p = 0.03) shortened the delirium period." (PMID 37374256, 2023). "Compared with other variables included in nutritional indices, only albumin showed a linear correlation with delirium." (PMID 36937934, 2023). "According to the increasing level of albumin, the occurrence of delirium tended to decrease linearly." (PMID 36937934, 2023). "Excessive hemorrhage, longer ICU stay, lower preoperative albumin and hemoglobin levels, and higher postoperative CRP levels were also risk factors for postoperative delirium in oral cancer surgery patients." (PMID 35465424, 2022). "The blood‐brain barrier (BBB) disruption contributes to postoperative delirium, and urine albumin to creatinine ratio (UACR), reflecting systemic vascular endothelial dysfunction." (PMID 34415671, 2022). "The logistic regression for group A shows that fluid intake (p = 0.02, OR = 5.27, 95% CI 1.27–21.8) and albumin levels (p = 0.036, OR = 0.22, CI 0.054–0.908) are independent predictors for the development of delirium." (PMID 35804948, 2022). "The logistic regression shows that fluid intake (p = 0.02, OR = 5.27, 95% CI 1.27–21.8) and albumin levels (p = 0.036, OR = 0.22, CI 0.054–0.908) are independent predictors for the development of delirium." (PMID 35804948, 2022). "The AUC of albumin, history of delirium, TSH, the resting score on the first postoperative day and age were 0.794, 0.754, 0.746, 0.721 and 0.689 respectively." (PMID 33678192, 2021).
delirium (continued). "And we have found that preoperative albumin, history of delirium, TSH, the resting score on the first postoperative day and age were the independent risk factors for the postoperative delirium in patients with hip fracture." (PMID 33678192, 2021). "At the same time, preoperative albumin, history of delirium, TSH, the resting score on the first postoperative day and age were the independent risk factors for the postoperative delirium in patients with hip fracture." (PMID 33678192, 2021). "The univariate analyses identified predictors of rehabilitation success, defined as MRFS R ≥ 50: age, TCS, MMSE, Norton score, serum albumin level, delirium rate, and periprosthetic fracture." (PMID 33163503, 2020). "Delirium is an important postoperative complication, which had prolonged hospitalization and high perioperative albumin infusion." (PMID 30049276, 2018). "This study investigated if the neutrophil percentage-to-albumin ratio (NPAR) could predict the onset of delirium in patients with cervical spinal cord injury (CSCI)." (PMID 41592020, 2026). "Given that serum albumin reflects not only nutritional status but also possesses antioxidant and neuroprotective properties, a lower albumin level at the time of injury may indicate an increased vulnerability to delirium development." (PMID 41592020, 2026). "Although short-term clinical outcomes, including transfusion rates, delirium, and length of hospital stay, were comparable, the significant improvement in serum albumin levels may suggest a potential advantage that could contribute to longer-term outcomes." (PMID 41375751, 2025). "TC, LDL-C, HDL-C, and albumin levels were significantly lower in the delirium group." (PMID 40573090, 2025). "PNI evaluates both serum albumin and lymphocytes, and these two biochemical parameters may have significant connections to the mechanism of delirium." (PMID 40765739, 2025). "Albumin and steroid use was observed in 23.2% and 26.4% of patients with delirium, respectively." (PMID 39679665, 2024). "Diverse studies have focused on the link between albumin levels and delirium." (PMID 38131687, 2023). "Predictive performances of nutritional indices for the occurrence of delirium were acceptable, and albumin alone as a component of nutritional indices might be a simple and helpful indicator of delirium in patients admitted to a CICU." (PMID 36937934, 2023). "Furthermore, albumin alone revealed an inverse linear correlation with delirium, and its predictive performance was superior to those of PNI and GNRI and similar to that of CONUT." (PMID 36937934, 2023). "Most importantly, a CDT value above 1.7%, CDT per percent increase, and Anttila-Index per unit increase remained significantly associated with delirium development in our multivariable models including the covariates SOFA-score, age, mechanical ventilation, and serum albumin." (PMID 37854697, 2023). "Analysis of risk factors for delirium showed that neither antipsychotic use, female gender, smoker, serum albumin content, nor BMI were risk factors for delirium in the inpatient setting." (PMID 36753475, 2023). "Higher blood albumin levels are also correlated to shorter delirium periods, maybe due to their role in buffering serum drug levels." (PMID 37374256, 2023). "As the feasibility of obtaining brain tissue for albumin detection is highly invasive and compromising, there is lack of direct shreds of evidence that can resolve the mystery regarding the association between BBB damage and delirium in clinical settings." (PMID 34415671, 2022). "In addition, patients with worse renal function or lower albumin are more likely to suffer from delirium, which has also been commonly reported in previous observations." (PMID 36468080, 2022).
delirium (continued). "The medical condition of the IR group was more complex, as reflected in a higher Charlson's comorbidity scores, higher rates for delirium and more infectious complications, a lower Norton score, lower serum hemoglobin, and albumin levels, and higher serum creatinine and urea levels." (PMID 33163503, 2020). "However, patients in the Delirium group exhibited higher postoperative bilirubin and creatinine levels (p < 0.0001) and lower postoperative protein (p = 0.002) and albumin (p = 0.019)." (PMID 32456289, 2020). "In addition, patients in delirium had prolonged hospitalization and high perioperative albumin infusion." (PMID 30049276, 2018). "Albumin alone might be a helpful and straightforward indicator for the occurrence of delirium." (PMID 36937934, 2023). "Therefore, albumin might be a helpful and simple indicator for predicting delirium in CICU patients." (PMID 36937934, 2023). "Urine albumin to creatinine ratio (UACR), reflecting systemic vascular endothelial dysfunction, may be a prognostic and predictive factor associated with postoperative delirium." (PMID 34415671, 2022). "Moreover, multivariate analysis reveals that in group A, low albumin and in group B, male gender and sedation duration could influence the occurrence of delirium." (PMID 35804948, 2022). "Furthermore, although levels of serum albumin and total protein were not identified as risk factors of postoperative delirium in logistic regression analysis, they were negatively correlated with filter metric." (PMID 27809817, 2016). "Biochemical markers indicated lower total protein (median 6.4, IQR 5.9-6.7 g/dL vs median 7.0, IQR 6.2-7.5 g/dL; P=.006) and albumin (median 3.6, IQR 3.1-3.9 g/dL vs median 4.1, IQR 3.2-4.4 g/dL; P=.004) levels in the delirium group." (PMID 39895101, 2025). "Participants in cluster 3 presented clinically orthogonally to cluster 1 (lower baseline cognition, higher frailty, more delirium, higher CRP and lower albumin)." (PMID 41462244, 2025). "There were statistically significant differences in race, SOFA score, heart rate, respiratory rate, body temperature, SpO2, ALB, WBC count, hemoglobin, blood urea nitrogen, anion gap, and INR between the delirium group and the non-delirium group (p < 0.05)." (PMID 40507679, 2025). "The primary outcome was the difference in serum albumin levels; secondary outcomes were the length of hospital stay (LOS), blood transfusions (Tf), and the incidence of delirium." (PMID 41375751, 2025). "By increasing nutritional intake and maintaining normal albumin levels in patients with dysphagia, we may be able to improve immune function, preserve neurological integrity, and facilitate tissue repair and regeneration, thereby potentially reducing the incidence of delirium." (PMID 38263028, 2024). "The pooled analysis of the included studies revealed that patients with higher preoperative CRP (SMD 0.43, 95% CI 0.19–0.67) or lower preoperative ALB levels (SMD ‐0.35, 95% CI ‐0.59 to ‐0.12) were more prone to develop delirium following TJA." (PMID 39259060, 2024). "The patients with and without delirium in both groups were compared regarding intraoperative fluid administration, fluid balance, and other parameters, such as blood loss, duration of surgery and overall ventilation, alcohol consumption, and creatinine, albumin, natrium, and hematocrit levels." (PMID 35804948, 2022). "This study aimed to investigate the relationship between serum C-reactive protein (CRP)/Albumin ratio (CAR) and postoperative delirium (POD) in patients older than 60 years following total knee arthroplasty (TKA)." (PMID 36051706, 2022). "Univariate logistic regression analysis revealed age, sex, albumin level, haemoglobin level, duration of ventilator intubation, APACHE II score, CRRT, NPPV, delirium, length of stay in the ICU, and timing of walking onset as independent variables for HAD." (PMID 36232218, 2022).
delirium (continued). "The differences in the rates of delirium, pressure ulcers, hematocrit (HCT) < 0.30, and low albumin (ALB), as well as the number of transfusions of red cells and plasma between the nonoperative group and arthroplasty group, was statistically significant." (PMID 32268893, 2020). "Delirium biomarkers that are included in standard blood examinations (i.e., albumin and creatinine) may be useful to attribute higher delirium risk but are not targets specific to delirium prevention since they are routinely addressed with respect to other clinical questions." (PMID 31263968, 2019). "Using propensity score matching (PSM) to balance baseline differences, we examined the magnitude of changes in serum albumin levels as the primary outcome and evaluated length of hospital stay (LOS), blood transfusions (Tf), and the incidence of postoperative delirium as secondary outcomes." (PMID 41375751, 2025). "Nevertheless, studies specifically addressing the influence of low albumin levels on the incidence of subsyndromal delirium following hip fractures in older adults are lacking." (PMID 41488107, 2025). "In a multivariable analysis including each component of nutritional indices, albumin was a significant predictor for delirium but not absolute lymphocyte count, bodyweight/ideal bodyweight, or total cholesterol level as a component of nutritional indices." (PMID 36937934, 2023). "Lastly, modifiable variables we included in the model (albumin level, number of drugs taken preoperatively) do not actually guarantee that modification of such variables will reduce the incidence of delirium." (PMID 35761274, 2022). "Monitoring albumin, TSH and resting score may be beneficial to the management of postoperative delirium." (PMID 33678192, 2021). "Less than 5% of the patients had leukocytosis, serum sodium or potassium abnormalities, or a low albumin level, and none of the patients with subsyndromal delirium had abnormal results for white blood cell, electrolyte, and albumin." (PMID 30053850, 2018). "In the comparison with the non-delirium group, patients with postoperative delirium had significantly lower levels of preoperative albumin and hemoglobin (P < 0.01)." (PMID 27881118, 2016). "Patients with postoperative delirium were significantly older, had lower preoperative hemoglobin levels and lower preoperative serum albumin levels than patients without postoperative delirium." (PMID 25189637, 2014). "Notably, the elevated NPAR in the delirium group appeared to be driven primarily by lower serum albumin levels rather than by an increase in neutrophil counts." (PMID 41592020, 2026). "Additionally, we incorporated established risk factors such as mechanical ventilation, age, and serum albumin, a strong predictor of ICU-delirium that is not included in the SOFA score." (PMID 37854697, 2023). "Furthermore, albumin, TC, HDL-C, and LDL-C levels were significantly lower, whereas creatinine, CRP, and N-terminal pro-brain natriuretic peptide (NT-proBNP) levels were significantly higher in the delirium group." (PMID 30413062, 2018).